BACE1-AS (BACE1 antisense RNA)
Synonyms: FJ573250; NCRNA00177; BACE1-AS1; BACE1AS
Gene: Long non-coding RNA gene on chromosome 11 (117,288,453 to 117,293,494, forward strand). Ensembl gene ENSG00000278768.
Diseases named in the same sentence as BACE1-AS in open-access papers:
BACE1-AS is named in the same sentence as 6 diseases in open-access papers, as found by Europe PMC text mining. Sharing a sentence is not in itself a finding about the gene and the disease. The quoted sentences say what the papers report.
Alzheimer disease (1 paper, 2024). A progressive, neurodegenerative disease characterized by loss of function and death of nerve cells in several areas of the brain leading to loss of cognitive function such as memory and language. "The dysregulation of BACE1AS is associated with upregulated BACE1 activity in several human disorders, including Alzheimer’s disease, Parkinson’s disease, heart failure, and MCI, indicating a potential influential role of BACE1AS in the progression of these diseases." (PMID 38543885, 2024).
amyloidosis (1 paper, 2020). A disorder characterized by the localized or diffuse accumulation of amyloid protein in various anatomic sites. "Based on our in vitro findings on the role of BACE-1AS in Tat-mediated induction of amyloidosis, we next sought to validate the expression of BACE1-AS RNA in the section of archival brains from patients infected with HIV." (PMID 32453744, 2020).
colon cancer (1 paper, 2018). "Enhanced expression of BACE1AS decreases the proliferation rate and invasiveness of ovarian cancer stem cells, however, in colon cancer, the expression of BACE1AS is significantly decreased." (PMID 30441874, 2018).
BACE1-AS also shares sentences with these, for which no sentence is quoted: heart failure (1 paper); ovarian carcinoma (1); Parkinson disease (1).